SFN (stratifin)
Diseases named in the same sentence as SFN in open-access papers (continued):
Sharing a sentence is not in itself a finding about the gene and the disease.
oral cancer (4 papers, 2018 to 2025). "In oral cancer, the SFN expression is influenced by Candida albicans." (PMID 36548207, 2022). "Decreased expression levels of stratifin occur frequently in many human cancers including breast, lung, colon, liver, prostate, ovary, nasopharynx, and oral cancers." (PMID 34372798, 2021).
prostate carcinoma (4 papers, 2010 to 2025). A carcinoma that arises from epithelial cells of the prostate gland. "Stratifin (14-3-3σ) is a member of the 14-3-3 gene family that regulates numerous cell pathways relevant to breast and prostate cancer including cell cycle arrest, signal transduction, apoptosis and proliferation." (PMID 20084286, 2010).
asthma (3 papers, 2021 to 2024). "Several genes such as SERPINE1, GPRC5A, SFN, ABCA1, MKI67, and RRM2 have been found to be downregulated in severe uncontrolled asthma using PBMCs and, therefore, potential biomarkers." (PMID 36294997, 2022). "Validation of the gene expression in PBMC of locally recruited asthma patients showed that SERPINE1, GPRC5A, SFN, ABCA1, MKI67, and RRM2 were downregulated in severe uncontrolled asthma." (PMID 34088958, 2021).
cholangiocarcinoma (3 papers, 2015 to 2022). A carcinoma that arises from the intrahepatic biliary tree (intrahepatic cholangiocarcinoma) or from the junction, or adjacent to the junction, of the right and left hepatic ducts (hilar cholangiocarcinoma). "Furthermore, silencing of SFN is associated with the upregulation of proapoptotic proteins (Bim and Bax) in cholangiocarcinoma cells, suggesting the oncogenic potential of SFN through inhibition of apoptosis." (PMID 36160032, 2022). "TTN-AS1 and SFN were highly expressed in cholangiocarcinoma, while miR-513a-5p showed low expression." (PMID 34903127, 2021). "miR-513a-5p was a regulator of cholangiocarcinoma through targeting SFN." (PMID 34903127, 2021).
endometrial cancer (3 papers, 2012 to 2023). Primary or metastatic malignant neoplasm involving the endometrium (mucous membrane that lines the endometrial cavity). "The higher expression of SFN was significantly associated with a better prognosis of endometrial cancer." (PMID 37033258, 2023). "Our finding showed that there was a reciprocal relationship between Sox7 and the levels of FGF9 and SFN which were 17.9-fold (P = 0.048) and 7.27-fold (P = 0.008), respectively, higher in endometrial cancer as compared with normal endometrium." (PMID 23295859, 2012). "Among them, we identified four genes (SFN, CDKN1A, GADD45G, and TP73) whose expression was positively correlated with endometrial cancer from TCGA data." (PMID 36358786, 2022).
metastatic cancer (3 papers, 2006 to 2025). A carcinoma which has spread from the original site of growth to another anatomic site. "We further observed that differences in nuclear and cytoplasmic SFN reactivity (p < 0.05 and p < 0.001, respectively) between the normal breast, primary cancer and metastatic cancer tissues were significant." (PMID 25167778, 2014). "In particular, SFN immunoreactivity scores within the stroma of normal breast tissue were significantly lower than the SFN immunoreactivity scores within stroma of primary (p < 0.05) and metastatic cancer tissues (p < 0.001)." (PMID 25167778, 2014). "However, a role for sFn in the etiology of metastatic cancer growth has not been extensively studied." (PMID 16925817, 2006).
pancreatic ductal adenocarcinoma (3 papers, 2020 to 2022). An infiltrating adenocarcinoma that arises from the epithelial cells of the pancreas. "A study on the molecular profiling of stroma in pancreatic ductal adenocarcinoma has revealed the upregulated expression of SFN, along with other genes." (PMID 35547358, 2022). "Similar to our results, studies have also reported that overexpression of SFN can be used as a better prognostic biomarker in gallbladder cancer and the stroma of pancreatic ductal adenocarcinoma (PDAC) treatment." (PMID 36160032, 2022). "Our current findings agreed with those of another study in which SFN was considered an independent prognostic biomarker in pancreatic ductal adenocarcinoma." (PMID 35547358, 2022).
schizophrenia (3 papers, 2020 to 2024). A major psychotic disorder characterized by abnormalities in the perception or expression of reality. "Furthermore, we established a schizophrenia diagnostic model based on genes associated with cellular senescence, which contain 6 candidate genes (SFN, KDM5B, MYLK, IRF3, IRF7, ID1)." (PMID 37113536, 2023). "Six candidate genes (SFN, KDM5B, MYLK, IRF3, IRF7, and ID1) were identified with diagnostic significance for schizophrenia." (PMID 37113536, 2023). "Moreover, an increased expression of SFN and decreased expression of YWHAB, YWHAE, YWHAG and YWHAQ mRNA have been reported in leukocytes of schizophrenia patients." (PMID 32545830, 2020). "Interestingly, five of these genes showed alterations in expression in both ASD and schizophrenia: YWHAB, YWHAE, YWHAH and YWHAZ showed decreased expression whether SFN showed increased expression in both disorders." (PMID 32545830, 2020).
Alzheimer disease (2 papers, 2021 to 2022). A progressive, neurodegenerative disease characterized by loss of function and death of nerve cells in several areas of the brain leading to loss of cognitive function such as memory and language. "SFN is abundant in neurons, and its abnormal expression and impaired function have been associated with the pathogenesis of Alzheimer’s disease, Parkinson’s disease, and MS." (PMID 33912166, 2021). "Furthermore, SFN could be positively implicated as an oncogene in a variety of diseases, including Alzheimer's disease, Parkinsonian syndromes, and autoimmune disorders affecting the central nervous system." (PMID 36160032, 2022).
bladder cancer (2 papers, 2008 to 2018). "CDH1 and SFN genes were methylated at high frequencies in bladder cancer as well as in paired normal adjacent tissue and exfoliated cells from cancer-free patients." (PMID 18702824, 2008). "Indistinct DNA hypermethylation of CDH1 and SFN genes between tumoral and normal urinary bladder samples suggests that these epigenetic features are not suitable biomarkers for urinary bladder cancer." (PMID 18702824, 2008). "Overall, these observations suggest that both genes, CDH1 and SFN, are not effective biomarkers for MSP analysis in bladder cancer." (PMID 18702824, 2008).
cervical squamous cell carcinoma (2 papers, 2019 to 2024). A squamous cell carcinoma arising from the cervical epithelium. "Importantly, the molecular mechanisms underlying the role of SFN in the progression of cervical squamous cell carcinoma remain unclear." (PMID 37946061, 2024). "It was spotted in TCGA database that SFN expression was dramatically upregulated in cervical squamous cell carcinoma and endocervical adenocarcinoma." (PMID 31779593, 2019). "Our findings revealed elevated expression of SFN in cervical squamous cell carcinoma tissues." (PMID 37946061, 2024).
colon cancer (2 papers, 2015 to 2022). "With the exception of SFN and MAPK13, all other genes were upregulated in colon cancer primary tumors compared with normal colon tissue and/or in colon cancer metastases compared with the primary tumor." (PMID 35565214, 2022).
liver cancer (2 papers, 2018 to 2021). An epithelial or non-epithelial malignant neoplasm that arises from the liver. "Moreover, the results of the present study showed that HOXA3 might interact with TRIM29, ENO1 and SFN, which was reportedly associated with the occurrence of liver cancer." (PMID 33683826, 2021).
melanoma (2 papers, 2022 to 2025). A malignant, usually aggressive tumor composed of atypical, neoplastic melanocytes. "The promoter of the SFN gene encoding the 14-3-3 σ protein is hypermethylated in melanocytes and melanoma cells, and p21 expression can be upregulated by 5-Aza treatment in melanoma cells." (PMID 35055045, 2022). "Risk forest plot analysis revealed that SFN, PLA2G4E, SERPINB5, WWC1, PAK6, and TEAD3 were the most influential genes in promoting melanoma malignancy." (PMID 41034991, 2025).
nasopharyngeal carcinoma (2 papers, 2022 to 2024). A carcinoma arising from the nasopharyngeal epithelium. "SFN (Stratifin), a cell cycle checkpoint protein, has been reported to be involved in tumorigeneses such as ovarian and nasopharyngeal cancer." (PMID 36092717, 2022).
oral squamous cell carcinoma (2 papers, 2022 to 2024). "In oral squamous cell carcinoma, SFN is overexpressed in cancer tissues and is associated with reduced overall survival, serving as an adverse prognostic indicator for oral squamous cell carcinoma." (PMID 37946061, 2024). "In oral squamous cell carcinoma, both SFN and cytoskeletal proteins are overexpressed and contribute to tumor development." (PMID 37946061, 2024). "In the future, we will further explore the mechanism of SFN involves in the oral squamous cell carcinoma carcinogenesis with C. albicans infection." (PMID 35563222, 2022).
osteosarcoma (2 papers, 2021 to 2025). A usually aggressive malignant bone-forming mesenchymal neoplasm, predominantly affecting adolescents and young adults.
ovarian serous adenocarcinoma (2 papers, 2019 to 2022). An adenocarcinoma that arises from the ovary and is characterized by the presence of malignant epithelial cells that, in well differentiated tumors, resemble the epithelium of the fallopian tube or, in poorly differentiated tumors, show anaplastic features and marked nuclear atypia. "High SFN expression is also associated with significantly worse OS for patients with ovarian serous adenocarcinoma who have received chemotherapy." (PMID 35936690, 2022). "Further analysis found that higher mRNA levels of SFN was associated with poorer OS of ovarian serous adenocarcinoma patients." (PMID 30926680, 2019). "Further analysis found that higher mRNA levels of SFN was associated with poor OS of ovarian serous adenocarcinoma patients." (PMID 30926680, 2019). "In addition, by log-rank tests in the Kaplan–Meier plots, we also discovered that ovarian serous adenocarcinoma cases with alterations in SFN gene had worse OS (P=0.0461)." (PMID 30926680, 2019).
Parkinson disease (2 papers, 2012 to 2021). A progressive degenerative disorder of the central nervous system characterized by loss of dopamine producing neurons in the substantia nigra and the presence of Lewy bodies in the substantia nigra and locus coeruleus. "SFN has been found to confer neuroprotection in animal models of Parkinson's Disease, ischemia, traumatic brain injury and glutamate excitotoxicity suggesting its potential use as a treatment for oxidative stress during HSV-encephalitis." (PMID 22558388, 2012).
psoriasis (2 papers, 2012 to 2020). An autoimmune condition characterized by red, well-delineated plaques with silvery scales that are usually on the extensor surfaces and scalp. "The proteins identified by LC–MS/MS, including SFN, GSTP1, FABP5, S100A7, and RABP2, were also observed to be upregulated in psoriasis lesional tissues." (PMID 32817748, 2020).
squamous cell carcinoma (2 papers, 2008 to 2015). A carcinoma arising from squamous epithelial cells. "SFN is downregulated in invasive bladder transitional cell carcinomas undergoing epithelial-to-mesenchymal conversion and highly upregulated in pure squamous cell carcinomas." (PMID 26230496, 2015).
thyroid cancer (2 papers, 2014 to 2025). "Moreover, FOS and JUN expression alterations in FTC, along with SFN upregulation in PTC, further highlight these genes as promising diagnostic candidates for specific thyroid cancer subtypes." (PMID 40722651, 2025). "In this study, we hypothesized that secretion of sFN in thyroid carcinoma cells’ ECM were caused by EMT, due to the fact that sFN was detected only in thyroid carcinoma cells, but not in normal thyroid cells and connective tissues." (PMID 24696692, 2014).
thyroid tumor (2 papers, 2014 to 2023). A benign or malignant neoplasm affecting the thyroid gland. "In conclusion, increasing the number of cells with sFN expression in thyroid tumors is correlated with lymph node metastasis, which suggests the malignancy of thyroid tumors." (PMID 24696692, 2014). "On the other hand, AHNAK2, GPX1, KRT19, and SFN show higher expression levels in thyroid tumors." (PMID 37795451, 2023).
Barrett esophagus (1 paper, 2018). Esophageal lesion lined with columnar metaplastic epithelium which is flat or villiform. "Based on previous studies investigating the role of BAK1, FIS1, and SFN, one primary function of these three genes in Barrett’s esophagus and in Barrett’s associated OAC may also be in conferring therapeutic resistance to cells; however, further studies are necessary to explore this relationship." (PMID 30404157, 2018).
basal cell carcinoma (1 paper, 2021). A carcinoma involving the basal cells.
cicatricial alopecia (1 paper, 2025). Scarring hair loss, also known as cicatricial alopecia, is the loss of hair which is accompanied with scarring. "In addition, our findings confirm the crucial role of CSNK1A1 and SFN in normal hair follicle development and their association with cicatricial alopecia." (PMID 41380997, 2025). "Our results showed that CSNK1A1 and SFN exhibit abnormal expression in the hair follicles of patients with cicatricial alopecia, indicating the possibly important role of CSNK1A1 and SFN in the normal developmental process of hair follicles." (PMID 41380997, 2025). "However, our results showed that the expression levels of CSNK1A1 and SFN were downregulated in cicatricial alopecia compared with the normal controls." (PMID 41380997, 2025). "We also found that CSNK1A1 and SFN exhibit abnormal expression in the hair follicles of patients with cicatricial alopecia, which further proves the role of CSNK1A1 and SFN in the normal development of hair follicles." (PMID 41380997, 2025). "Downregulation of SFN and CSNK1A1 may serve as potential biomarkers for studying cicatricial alopecia and provide clues for understanding its molecular mechanisms." (PMID 41380997, 2025). "Notably, this study indicates that CSNK1A1 and SFN exhibit abnormal expression in the hair follicles of patients with cicatricial alopecia, which further validates the role of CSNK1A1 and SFN in the normal developmental process of hair follicles." (PMID 41380997, 2025).
ciliopathies (1 paper, 2016). "In the context of proteasomal activity, SFN is a promising therapeutic agent for ciliopathies and any form of cancer in which proteasomal activity is reduced." (PMID 27293550, 2016).
Cirrhosis (1 paper, 2017). A chronic disorder of the liver in which liver tissue becomes scarred and is partially replaced by regenerative nodules and fibrotic tissue resulting in loss of liver function. "Compared with patients without cirrhosis, the expression of CDK7 was downregulated in patients with cirrhosis, whereas the expression of SFN was upregulated in patients with cirrhosis." (PMID 28266596, 2017).
colitis (1 paper, 2023). Inflammation of the colon. "In mice, adaptive transfer of SFN+/+ pre-treated DCs protected the animals from colitis compared to those that had received SFN−/− pre-treated DCs." (PMID 36986896, 2023).
diabetes (1 paper, 2015). "The proteasome activator SFN has been suggested in studies as a possible therapeutic treatment for various diabetes conditions such as nephropathy and aortic damage." (PMID 26064977, 2015).
esophageal cancer (1 paper, 2025). A primary or metastatic malignant neoplasm involving the esophagus. "Regarded as a tumor suppressor, the SFN expression has been shown to be downregulated in several carcinomas, including lung, breast, and esophageal cancer." (PMID 40004538, 2025).
follicular carcinoma (1 paper, 2025). "Specifically, noteworthy are our findings regarding the potential diagnostic value of CCNA1 and SFN genes in papillary thyroid carcinoma, while the reduced expression of CDKN1C, FOS, and JUN genes in follicular carcinoma suggests their value in distinguishing the thyroid pathologies." (PMID 40722651, 2025).
gastric cancer (1 paper, 2024). A primary or metastatic malignant neoplasm involving the stomach. "In gastric cancer research, a positive correlation between SFN and Ki-67 suggests the crucial role of SFN in gastric cancer cell proliferation." (PMID 37946061, 2024).
intervertebral disc degeneration (1 paper, 2025). "The altered expression of SFN may be a key factor in intervertebral disc degeneration at high altitudes." (PMID 41458156, 2025).
intrahepatic cholangiocarcinoma (1 paper, 2025). A carcinoma that arises from the intrahepatic bile duct epithelium in any site of the intrahepatic biliary tree. "In addition, Gem and SFN-mediated HDAC inhibition caused increased Bax expression and decreased Bcl-2 expression in intrahepatic cholangiocarcinoma HuCCT-1 and HuH28 cells." (PMID 40006525, 2025).
keloid (1 paper, 2023). An irregularly shaped, elevated mark on the skin caused by deposits of excessive amounts of collagen during wound healing. "After that, in differentiation stage, antifibrinogenic factor such as stratifin will be released, so that avoid over healing and keloid." (PMID 35817088, 2023).
lung fibrosis (1 paper, 2023). "During the period of lung fibrosis, several intermediate AECII was detected by specific markers such as keratin 8 (KRT8), claudin 4 (CLDN4) and stratifin (SFN)." (PMID 37161570, 2023).
major depressive disorder (1 paper, 2025). An episode of depression lasting two or more weeks without an intervening episode of mania. "Finally, we observed a differential expression of iRNAPII-BRs and nearby genes—ADRB2, CXCL8, SFN, and GPR3—in major depressive disorder, indicating that iRNAPII-BR-associated transcription may contribute to the pathophysiology of this disorder." (PMID 41446805, 2025).
mastitis (1 paper, 2021). Inflammation of breast tissue during lactation or postpartum due to an obstructed duct or infection. "SFN was reported to regulate cell cycle progression in bovine mastitis via genome-wide association." (PMID 34691146, 2021).
meningioma (1 paper, 2017). A generally slow growing tumor attached to the dura mater. "NME1, NFE2, SFN, PTN, CALN1, GABRA5 and several components involved in neural differentiation and receptors associated with neural transmitter were also found to illicit an autoimmune response in the meningioma patients indicating that there could be some alterations in these components." (PMID 28938569, 2017).
multiple myeloma (1 paper, 2021). "Overexpression of SFN in multiple myeloma cells attenuated arsenic trioxide-induced cell death." (PMID 34899304, 2021).
ovarian serous cystadenocarcinoma (1 paper, 2019). A malignant serous cystic epithelial neoplasm arising from the ovary. "Using UALCAN database, we analyzed the expression profiles of SFN in normal and ovarian serous cystadenocarcinoma samples based on clinicopathologic parameters, such as cancer stage, age, race, and tumor grade." (PMID 30926680, 2019). "And for cancer grades, the expression level of SFN was higher in grade 3 compared with the grade 2 of ovarian serous cystadenocarcinoma." (PMID 30926680, 2019). "And for cancer grades, the expression level of SFN was higher in grade 3 compared with the grade 2 of ovarian serous cystadenocarcinoma (P<0.05)." (PMID 30926680, 2019).